EGFR (epidermal growth factor receptor)
Diseases named in the same sentence as EGFR in open-access papers (continued):
Sharing a sentence is not in itself a finding about the gene and the disease.
tumor (continued). "In this study, tumor-targeted liposomes containing Q-dots and siRNA molecules were prepared and then coupled to anti-EGFR aptamers." (PMID 28842588, 2017). "CRIS-C categorizes tumours that are strictly dependent on EGFR signals and are sensitive to treatment with anti-EGFR antibodies." (PMID 28561063, 2017). "It was recently published that cetuximab upregulates the CD137 expression on human NK cells after in vitro incubation with tumor cells expressing EGFR." (PMID 28674498, 2017). "Accordingly, the aim of this study was to investigate the prognostic value and tumor expression patterns of EGFR, uPAR and TF in OSCC." (PMID 28841839, 2017). "Together, the failure to readily overcome EGFR inhibitor resistance signifies the importance of identifying means of inhibiting the initial development of resistance in these tumours with effective up-front combination therapy." (PMID 28059068, 2017). "Unfortunately, the low number of patients with EGFR mutant tumor exclude us from studying potential role of high MET expression as a potential negative predictive marker in first line EGFR TKI therapy." (PMID 28915692, 2017). "Analysis of the tumor tissues indicated that the relative levels of EGFR mRNA transcripts in the XWLC-05-miR-370 tumors were significantly lower than XWLC-05-miR-NC tumors." (PMID 29152147, 2017). "Among 80 tumor-tissue EGFR M+ patients treated with EGFR-TKIs, the median PFS of plasma EGFR M+ patients was shorter than that of plasma EGFR M- patients, but the difference was not significant (334 days vs. 420 days, P = 0.145)." (PMID 28052016, 2017). "As EGFR signaling is highly mitogenic for intestinal epithelial stem cells, and plays essential roles in intestinal epithelial regeneration and tumor development, we have now examined the role of PACS-2 in these processes." (PMID 29312533, 2017). "Tumor samples were available from 51% of study participants, of which 37.3% (208 patients) were EGFR FISH positive." (PMID 29246028, 2017). "Results showed a significant upregulation of Ki67 and EGFR in the tumour tissues stably overexpressing miR-18a, accompanied by reduction of E-cadherin expression." (PMID 28471447, 2017). "In fact, the expression of AREG and EREG is coordinately regulated, and plays an important role in tumor growth and survival by generating an autocrine loop through EGFR." (PMID 28002810, 2017). "Together, our data support the clinical evaluation of KTN3379 in HNSCC and provides a scientific rationale that supports the combination of EGFR and ErbB3-targeting mAbs for the treatment of this tumor type." (PMID 28723928, 2017). "We observed that across all tumor cell lines, afatinib more effectively inhibited EGFR activation compared to erlotinib." (PMID 28423495, 2017). "BMI, sex, DM, ECOG PS, EGFR mutant status, tumor type, LMR, DLM were predictive factors in univariate analysis." (PMID 28591157, 2017). "The transcription of PKM2- dependent β-catenin is required for EGFR promotion of tumour cell proliferation and tumour development." (PMID 29127353, 2017). "In three cases (#5, 15, 19) EGFR-targeted therapy was given prior to resection of the primary tumor (#5), recurrent tumor (#19) or liver metastasis (#15)." (PMID 28199979, 2017). "For example, the receptor tyrosine kinase EGFR exhibits altered expression in several types of solid tumors and its overexpression in UC is directly correlated with advanced tumor stages." (PMID 29379438, 2017). "Clinically, EGFR kinase inhibitors and blocking antibodies are available; however, resistance to these anti-tumor therapies is common, leading to highly invasive and metastatic tumor outgrowth." (PMID 28978320, 2017). "Cisplatin-resistant tumors showed improved tumor inhibition with EGFR-targeted combination therapy, which showed reduced toxicity to normal tissues." (PMID 28290155, 2017). "Inhibition of this protease with a selective small molecule inhibitor was further found to impede CRC tumor growth by targeting the EGFR axis." (PMID 29029414, 2017).
tumor (continued). "UVB-induced AhR activation upregulates suppression of reversible tumor promotion before tumor the RAF-MEK1/2-ERK1/2 signaling pathway via c-Src-dependent EGFR activation, and when AhR is activated, it upregulates its specific target gene, cyp1a1." (PMID 29285309, 2017). "According to this system, specimens with ≥ 4 copies of EGFR signal in ≥ 40% cells, or ≥ 4 spots of gene clusters or ≥ 10% of tumor cells with ≥ 15 copies of EGFR signals or an EGFR/CEP7 ratio ≥ 2 were classified as positive for EGFR." (PMID 29246028, 2017). "By inhibiting the over-expression of EGFR, they help to restrict the growth, invasion and metastasis of tumor." (PMID 28460479, 2017). "Oncogenic EGFR and PDGFR signalling mechanisms are important contributors to tumour growth and invasion in GBM, and NF-κB is implicated in at least some of the tumour promoting functions of these receptors." (PMID 28598356, 2017). "TPS≥1% for PD-L1 and low CD8+ TIL in post-TKI tumor showed a trend for a lower PFS of EGFR-TKIs (14.2 vs 9.9 months; P = 0.060) (cohort A)." (PMID 29296194, 2017). "In vivo, studies with human tumor xenografts also confirmed remarkable antitumor activity as well as selectivity over wild-type EGFR." (PMID 28881827, 2017). "Recently, right-sided location of the primary tumor has been reported to negatively influence treatment benefit of anti-EGFR mAb." (PMID 28695301, 2017). "EGFR activation enhanced the level of plasma membrane BCRP in head and neck squamous cancer cells, and accordantly, treatment with EGFR inhibitor erlotinib reversed tumor resistance to topotecan by reducing the expression of BCRP/ABCG2." (PMID 29291022, 2017). "Activation of EGFR on tumour cells by EGF in turn upregulated VEGF/VEGFR signalling in surrounding tumour cells to support tumour cell proliferation and migration." (PMID 29065107, 2017). "We found that the protein levels of ZNF516 were lower in tumor samples than in adjacent tissues, whereas the levels of EGFR showed an inverse trend." (PMID 28947780, 2017). "Distribution of EGFR reactivity and polysomy/amplification was similar between different tumour sizes." (PMID 28377929, 2017). "Two meta-analyses suggested that primary tumours in the right-sided colon showed worse prognoses than those in the left-sided colon and rectum in patients treated with anti-EGFR antibodies." (PMID 28972961, 2017). "To date, there is no approved predictive biomarker able to predict tumor sensitivity to EGFR‐TKI since most of the resistance mechanisms are acquired during tumor treatment." (PMID 28003335, 2017). "PCR-based methods such as bead-based digital PCR in emulsions (BEAMing) and droplet-based digital PCR have been used to detect highly recurrent tumor-specific mutations in well-known driver genes such as APC, BRAF, KRAS and EGFR in plasma samples." (PMID 29156805, 2017). "Based on these results, the NCCN guidelines have also now recommended that the anti-EGFR antibodies be used only for left-sided tumours." (PMID 28386297, 2017). "In summary, the results of the present study confirm that BEAMing is a high-efficiency method for tumor genotyping and for evaluating resistance to anti-EGFR treatment." (PMID 27852040, 2017). "Four preclinical studies evaluated anti-EGFR antibodies or EGF labeled with a fluorescent compound to discriminate tumor cells from adjacent brain tissue." (PMID 27878374, 2017). "The development of novel molecular-targeted anti-tumor drugs that can target the interior of tumor cells and specifically silence EGFR expression is valuable and promising." (PMID 28181832, 2017). "Preclinical data have demonstrated that combined inhibition of IGF-1R and EGFR resulted in an enhanced anti-tumor effect in xenograft models." (PMID 28002810, 2017). "Induction of RanBP6-V5 also reduced tumor growth and EGFR expression in subcutaneous TS516 xenografts." (PMID 29229958, 2017). "Samples were collected 1, 2 and 24 h after EGFR-TKI administration on day 40 after tumor implantation." (PMID 29228726, 2017).
tumor (continued). "Among six patients, five patients had available information about T790M status of their tumor by conducting pre- or post-biopsy of tumor tissue when patients developed disease progression against preceding EGFR-TKIs therapy." (PMID 28144730, 2017). "In this study, we first evaluated EGFR gene and protein expression in 70 Chinese EC patient tumor samples collected during surgery." (PMID 28881608, 2017). "Taken together, our findings suggest that miR-34a inhibits NSCLC tumor growth and metastasis through targeting EGFR." (PMID 28825720, 2017). "For example, mutations in EGFR and MLL2 were private to 327_T_PDO, whereas tumour 278_T and its models diverged for mutations in FAM123B, MTOR, and for a PTCH1 frameshift mutation predicted to activate oncogenic sonic hedgehog signalling." (PMID 28186126, 2017). "By instead culturing the cells in FGF-2 (no EGF) we show that the amplification was retained at passage 15 and thus constitute an appropriate model system to study EGFR-amplified pediatric GBM tumor cells." (PMID 28148893, 2017). "In vitro cytotoxicity of CART-EGFR cells was tested by co-culturing with EGFR-positive tumor cells at various effector-to-target ratios in 96-well plates using a 4-h CCK-8 Detection kit (DOJINDO, Japan)." (PMID 28057014, 2017). "Historically the coexistence of EGFR mutations and EML4-ALK rearrangements in the same tumor has been described as virtually impossible." (PMID 28938691, 2017). "We also assessed which of the known cancer drivers, KIT, EGFR or MYC, had the closest association with tumor progression." (PMID 29088714, 2017). "The predictive relevance of primary tumor sidedness has been specifically demonstrated with regard to monoclonal antibodies targeting the epidermal growth factor receptor (EGFR-mAb)." (PMID 29285289, 2017). "In vitro uptake studies were perfomed on tumor cell overexpressing EGFR and showed that GE11-targeted polymer micelles were uptaken significantly faster with respect to the micelles without GE11 linkage." (PMID 29271876, 2017). "Numerous reports have shown that anti-EGFR treatment can inhibit tumor cell survival, growth, proliferation and differentiation." (PMID 28445956, 2017). "In this study, EGFR-MBs were directly injected into the tumor region, and BLM was injected via the tail vein." (PMID 28938010, 2017). "Clopidogrel treatment suppressed PMPA in vitro, suppressed growth of PC-10 tumour xenografts in vivo, and moderately abrogated EGFR phosphorylation in the tumour xenograft." (PMID 28642617, 2017). "The single tumor which was resistant to afatinib plus cetuximab represented a particular EGFR-refractory case." (PMID 28416737, 2017). "The inhibition of either EGFR or focal adhesion kinase, or performing a dynamic reduction in tumor microenvironment matrix stiffness, significantly slowed tumor growth of the EGFR mutants." (PMID 30920523, 2017). "In this cohort, Giannikopoulus and colleagues demonstrated the presence of SMO gene amplification in tumor biopsies taken at occurrence of resistance to EGFR-TKIs in 12,5% patients concomitantly with MET gene amplification." (PMID 28416737, 2017). "Western blot analysis of tumor tissues also showed that total EGFR, C-Raf, AKT and their phosphorylated forms were significantly decreased in all FM807-treated groups." (PMID 28157708, 2017). "The cut-off point of EGFR positivity (defining “high gene copy number”) was previously determined as ≥4 EGFR copies in ≥40% of tumor cells, or numerous gene clusters observed in at least 10% of tumor cells." (PMID 27924059, 2017). "Compared with EGFR, the detection of BRAF mutation both in tumor tissue and plasma still has a long way to go." (PMID 28572536, 2017). "Increasing our understanding of the mechanisms that tumor cells use to escape immunosurveillance will allow strategies to reverse EGFR mediated immune escape." (PMID 28611673, 2017).
tumor (continued). "Intriguingly, recurrent tumor tissues revealed elevated levels of activated EGFR compensating for FGFR1 inhibition." (PMID 28775339, 2017). "The rE/CUS significantly inhibited the cell viability against EGFR over expression tumor cell lines in a dose-and time-dependent manner." (PMID 28445134, 2017). "In a glioblastoma multiforme mouse xenotransplant model, a minor mutant EGFR subpopulation enhanced tumourigenicity of the entire tumour." (PMID 28716075, 2017). "Numerous synergies established between EGFR and c-Src and responsible for an increased tumor growth have also been described, strengthening the necessity to target these two proteins in tandem." (PMID 28446239, 2017). "Despite high tumor response rates with first-line EGFR-TKIs, disease progresses in a majority of patients after 9 to 13 months of treatment." (PMID 28903458, 2017). "The registration of the PET and CT images showed the localization of most remaining activity in the tumor region revealing targeting of EGFR-expressing UM-UC-3LUCK1 cells." (PMID 29169339, 2017). "Our studies are in accordance with previous studies, which showed that CNR2 agonists inhibit the tumor growth and metastasis through induction of apoptosis and inhibition of EGFR activation in non-small cell lung cancer (NSCLC)." (PMID 27213582, 2017). "These inhibitors display high-EGFR T790M-mutant selectivity and irreversible binding patterns while sparing the wild-type EGFR activity, thus enhancing tumor selectivity while minimizing adverse effects." (PMID 29238696, 2017). "The reduced liver binding of 57Co-DOTA-ZEGFR:2377 makes it more available for binding to EGFR-expressing tumours and tissues, which is in agreement with experimental observations." (PMID 28729680, 2017). "Characteristics of tumor microenvironment have been suggested as predictive markers of anti-EGFR or anti-HER2 treatment response." (PMID 28969039, 2017). "We then analyzed RHOB expression on tumor biopsies of patients receiving EGFR‐TKI as a first‐line or as second‐ to fourth‐line therapy." (PMID 28003335, 2017). "It has been reported that a mechanism of acquired resistance to EGFR inhibitors is mediated by the increased secretion of VEGF, suggesting a key role for tumor-induced angiogenesis in the development of anti-EGFR resistance." (PMID 29270405, 2017). "Generally, the anti-tumor efficacy of theliatinib correlated with the level of EGFR expression in PDECX models." (PMID 28881608, 2017). "Consistent with the low overall concordance we observed between cfDNA and tumor tissue NGS data, only one actionable mutation was detected in the same patient by both assays, an EGFR amplification in patient pan-545." (PMID 29137355, 2017). "BAX69 abrogates MIF signaling and MIF-mediated secretion of cytokines (IL-1β, TNF-α, etc.)and inhibits proliferation of MIF overexpressing tumor cells, together with the antiproliferative effects of panitumumab (anti-EGFR mAb)." (PMID 29312320, 2017). "Both groups showed that the efficacy of BRAF inhibitor is improved greatly in vitro when combined with an EGFR inhibitor and that this combined treatment leads to tumour regression in vivo." (PMID 28282860, 2017). "The CRT regimen currently employed has been shown to activate EGFR signaling and to enrich and induce CSCs leading to tumor recurrence." (PMID 28423495, 2017). "Coupling of aptamer molecules against the EGF receptor (EGFR) to the distal termini of lipid nanoparticles provided the carrier with tumor-specific recognition capability." (PMID 28842588, 2017). "Because hyperplasia in RA is similar to a hyperplastic tumor, scientists believe that EGFR has a role to play in RA pathology." (PMID 28700691, 2017). "We present here the final results of this trial, together with molecular analysis of EGFR, KRAS and BRAF mutation status in the tumor." (PMID 27924059, 2017). "Inhibition of PTGS2 or EGFR signaling is known to sensitize tumor cells to TNFSF10-mediated apoptosis." (PMID 28686677, 2017).
tumor (continued). "KRAS and NRAS mutations are the most extensively investigated somatic mutations in metastatic colorectal cancers, and they predict tumor resistance to anti-EGFR therapy, such as cetuximab and panitumumab." (PMID 28993799, 2017). "Anti-EGFR nanobody-targeted polymeric micelles containing doxorubicin were significantly more effective at inhibiting tumor growth and prolonging the survival of animals compared with untargeted micelles." (PMID 29213270, 2017). "Recent studies in a number of different mouse tumor models have revealed that EGFR-mediated signaling, specifically within macrophages, substantially contributes to the initiation of tumor growth." (PMID 28970798, 2017). "Increased c-Cbl levels were also dramatically increased by doxycycline in flank tumor xenografts of HSC3/EGFR-GFP/tet-Cbl cells in vivo." (PMID 29268862, 2017). "Although EGFR has been successfully used as a therapeutic target for many tumor types, unencouraging results have been obtained in clinical trials (in both mono- and adjuvant therapy protocols) conducted in TNBC patients." (PMID 29115931, 2017). "EGFR TIKs show dramatic tumor response and favorable clinical outcomes via competitively inhibiting the tyrosine kinase domain of EGFR." (PMID 28415568, 2017). "siRNA was employed to decrease the multidrug resistance of the targeted laryngeal tumor, while GE11 actively targeted the liposomes to the tumor cells overexpressing EGFR." (PMID 29271876, 2017). "On the other hand, EGFR-TKIs were reported to inhibit both tumor cells and the crosstalk between tumor cells and bone matrix cells." (PMID 29113396, 2017). "NSC released anti-EGFR Nbs can inhibit EGFR signaling dramatically in vitro and reduced the tumor growth in mice bearing GBM." (PMID 29163515, 2017). "The expression of Ki67, E-cadherin and epidermal growth factor receptor (EGFR) in the xenograft tumour tissues were measured using immunohistochemistry." (PMID 28471447, 2017). "In summary, we observed expression of EGFR in 37% of tumours with low malignant potential and in 40% of tumours with high malignant potential." (PMID 28377929, 2017). "The LARLLT and YHWYGYTPQNVI targeting sequences have been shown to promote uptake of nanoparticles to tumour cells overexpressing EGFR." (PMID 28166195, 2017). "A reciprocal relationship between loss of Dsg1 and neddylated EGFR was observed in a carcinoma model, consistent with a role in sustaining EGFR activity during tumor progression." (PMID 28891468, 2017). "Consequentially, abnormal expression of EGFR results in tumour cell proliferation, angiogenesis, invasion, metastasis and inhibition of apoptosis." (PMID 28832323, 2017). "Knocking down YAP1 in H1975, HCC827 or PC9 cells resulted in significant inhibition of cell proliferation, indicating that YAP1 plays a role in the growth of EGFR-mutant tumor cells." (PMID 29163769, 2017). "Sr-exosomes of tumour-implanted mice were isolated and EGFR is highly expressed in the sr-exosomes of tumour-implanted mice, but not in the control group." (PMID 28393839, 2017). "Analyses revealed a reduced EGFR phosphorylation level in tumor homogenates derived from MAG-EPA-treated mice comparatively to control mice." (PMID 28869531, 2017). "In the current study, we also observed a strong correlation between high BRCA1 expression and the basal cell nature of the tumor (positive for EGFR and/or CK5/6)." (PMID 28863181, 2017). "Only one patient with common EGFR gene mutation (with deletion in exon 19) expressed PD-L1 on 70% (22C3 clone) and 4% (SP142 clone) of tumor cells in both IHC assays." (PMID 28969070, 2017). "In fact, in this type of cancer EGFR is considered one of the most potent driver in tumour development in about 15–20% of cases and for which targeted therapies have been developed and introduced with success into the clinical setting." (PMID 29088281, 2017).